TMEM68 (transmembrane protein 68)
Description:
Catalytic subunit of the alternative triglyceride biosynthesis pathway, which mediates formation of triacylglycerol from diacylglycerol and membrane phospholipids. Synthesizes triacylglycerol at the expense of membrane phospholipids, such as phosphatidylcholine (PC) and its ether-linked form (ePC), thereby altering the composition of membranes. The alternative triglyceride biosynthesis pathway is probably required to provide the energy required for rapid growth when fuel sources are limiting. It maintains mitochondrial function during periods of extracellular lipid starvation. Can also use acyl-CoA as donor: acts as a acyl-CoA:monoacylglycerol acyltransferase (MGAT), but also shows acyl-CoA:diacylglycerol acyltransferase (DGAT) activity (By similarity).
Synonyms: DIESL; MGAT/DGAT; FLJ32370
Tractability: Antibody: UniProt predicts a signal peptide or a membrane-spanning region. PROTAC: ubiquitination databases record sites on it; its protein half-life has been measured.
Gene: Protein-coding gene on chromosome 8 (55,696,424 to 55,773,407, reverse strand). Ensembl gene ENSG00000167904.
Subcellular location: Endoplasmic reticulum membrane
Subcellular location (Human Protein Atlas): Vesicles
Gene Ontology:
Molecular function: phospholipid:diacylglycerol acyltransferase activity; 2-acylglycerol O-acyltransferase activity; diacylglycerol O-acyltransferase activity; acyltransferase activity
Biological process: triglyceride biosynthetic process
Cellular component: endoplasmic reticulum membrane; membrane
Genetic constraint (gnomAD): Loss-of-function variants: 20 observed, 30.84 expected, observed/expected ratio (o/e) 0.65, 90% interval 0.46 to 0.94. The upper end of that interval is the gene's LOEUF score, 0.94, which puts it in group 3 of 6, group 1 being the genes least tolerant of losing a copy. Missense variants: 292 observed, 367.21 expected, observed/expected ratio (o/e) 0.8, 90% interval 0.72 to 0.88. Synonymous variants: 118 observed, 119.35 expected, observed/expected ratio (o/e) 0.99, 90% interval 0.85 to 1.15.
Homologues: Orthologues: chimpanzee TMEM68 (99% identical), macaque TMEM68 (99% identical), dog TMEM68 (98% identical), rabbit TMEM68 (96% identical), pig TMEM68 (96% identical), rat Tmem68 (93% identical), mouse Tmem68 (93% identical), guinea pig TMEM68 (93% identical), zebrafish tmem68 (69% identical), tropical clawed frog tmem68 (68% identical), Caenorhabditis elegans Y38C1AA.1 (45% identical), Drosophila melanogaster CG34348 (45% identical).
Diseases named in the same sentence as TMEM68 in open-access papers:
TMEM68 is named in the same sentence as 2 diseases in open-access papers, as found by Europe PMC text mining. Sharing a sentence is not in itself a finding about the gene and the disease. The quoted sentences say what the papers report.
breast carcinoma (2 papers, 2019 to 2023). "Collectively, this study presents novel evidence suggesting that TMEM68, IMPAD1, SDCBP, and RBM12B are potential modifiers of human breast cancer risk and outcome." (PMID 30914425, 2019). "In addition, when TMEM68 and mtTMEM68 were expressed in parallel in human breast cancer MCF-7 cells, TG levels in TMEM68-expressing but not in mtTMEM68-expressing cells were significantly elevated compared with non-transfected MCF-7 cells." (PMID 36768334, 2023).
TMEM68 also shares sentences with these, for which no sentence is quoted: tumor (2 papers).